FAM3C (FAM3 metabolism regulating signaling molecule C)
Diseases named in the same sentence as FAM3C in open-access papers (continued):
Sharing a sentence is not in itself a finding about the gene and the disease.
endometriosis (2 papers, 2021 to 2024). The growth of functional endometrial tissue in anatomic sites outside the uterine body. "We also identified putative inhibitory interactions between endometriosis immune cells and ectopic FBs rather than eutopic FBs, including KLRB1, TIGIT, and PDCD1, which were highly expressed by NK and T cells, and potentially bind to CLEC2D, NECTIN3, and FAM3C, which were expressed by FBs." (PMID 34233737, 2021).
esophageal squamous cell carcinoma (2 papers, 2015 to 2025). Esophageal squamous cell carcinoma (ESCC) is a type of esophageal carcinoma (EC) that can affect any part of the esophagus, but is usually located in the upper or middle third. "Similarly, elevated FAM3C is strongly linked to poor prognosis in various cancers, including liver, colorectal, gastric, breast, esophageal squamous cell carcinoma, and oral squamous cell carcinoma." (PMID 40110195, 2025). "However, the role of FAM3C in esophageal squamous cell carcinoma (ESCC) remains unexplored." (PMID 26498278, 2015).
glioma (2 papers, 2022 to 2024). A benign or malignant brain and spinal cord tumor that arises from glial cells (astrocytes, oligodendrocytes, ependymal cells). "Subsequent experiments conducted on glioma cell lines, tumor tissues, and mouse models reinforced the close association of FAM3C with processes including glioma cell proliferation, cell cycle progression, apoptosis, and invasion." (PMID 39629744, 2024). "While insufficient data preclude a direct association between FAM3C alteration and glioma patients' prognosis, the potential oncological role of FAM3C in gliomas has been implicated." (PMID 39629744, 2024). "In order to study the relationship between FAM3C and glioma‐associated EMT, we conducted knockdown and overexpressed experiments targeting FAM3C in U87 and U251 cells." (PMID 39629744, 2024). "Notably, high mRNA expression of FAM3C was found to be independently associated with significantly shorter overall survival in glioma patients, even after accounting for clinical variables such as World Health Organization classification, tumor type, chemotherapy, and 1p19q status." (PMID 39629744, 2024). "Clinical data showed that glioma patients with FAM3C amplification had shorter disease/progression‐free intervals and overall survival compared to those without such amplification." (PMID 39629744, 2024). "Survival prognosis analysis based on GEPIA and CGGA data consistently indicated that high FAM3C expression correlated with a shorter survival time in glioma patients." (PMID 39629744, 2024). "In order to delve deeper into the biological role of FAM3C in glioma cells, we overexpressed FAM3C in both the U87 and U251 cell lines, confirming the efficiency of overexpression through qRT‐PCR and western blotting." (PMID 39629744, 2024). "Subsequently, to assess the impact of FAM3C on the malignant phenotype of gliomas, we conducted a series of functional assays." (PMID 39629744, 2024). "The expression level of FAM3C correlated with the progression of glioma grade and served as a prognostic indicator for poor patient outcomes." (PMID 39629744, 2024). "Both in vivo and in vitro analyses revealed a significant upregulation of FAM3C expression in gliomas." (PMID 39629744, 2024). "Subsequently, to assess the impact of FAM3C on malignant phenotypes of gliomas, we performed a battery of functional assays." (PMID 39629744, 2024). "Collectively, these data suggest FAM3C in driving epithelial mesenchymal transition in gliomas through the modulation of the Notch signaling pathway." (PMID 39629744, 2024). "Utilizing qRT‐PCR and western blotting, we assessed FAM3C expression levels in glioma tissues and normal brain samples." (PMID 39629744, 2024). "In summary, our findings demonstrated that FAM3C knockdown effectively restrains the proliferation and invasion and augments the apoptotic capabilities of glioma cells." (PMID 39629744, 2024). "In essence, our findings suggest that the overexpression of FAM3C significantly augments the proliferative and invasive capacities and decreases the apoptotic capacities of glioma cells." (PMID 39629744, 2024). "In summary, these in vivo findings further indicate the role of FAM3C‐mediated Notch signaling pathway in glioma proliferation and epithelial mesenchymal transition." (PMID 39629744, 2024). "Consistently, similar observations were made in U251 cells, further underscoring the role of FAM3C in promoting these malignant phenotypes in glioma cells." (PMID 39629744, 2024). "Following this, glioma tissues were obtained from resected specimens of patients to assess the expression of FAM3C and molecular markers related to epithelial–mesenchymal transition (EMT) and Notch signaling pathways." (PMID 39629744, 2024). "Our study reveals that silencing FAM3C gene mediates the Notch pathway, impacting glioma cell proliferation, invasion, apoptosis, and epithelial mesenchymal transition." (PMID 39629744, 2024). "We proceeded to investigate the biological functions of FAM3C in gliomas." (PMID 39629744, 2024).
glioma (continued). "Herein, we aimed to further investigate the oncological mechanism of FAM3C, specifically in glioma." (PMID 39629744, 2024). "Thus, the expression level of FAM3C emerges as a robust independent prognostic factor for glioma patients." (PMID 39629744, 2024). "Furthermore, qRT‐PCR analysis conducted on glioma cell lines demonstrated elevated FAM3C expression levels relative to normal brain cell lines, with the highest expression observed in the U87MG cell line." (PMID 39629744, 2024). "Similarly, consistent results were observed in U251 cells, further highlighting the role of FAM3C in promoting this malignant phenotype in glioma cells." (PMID 39629744, 2024). "Finally, a mouse subcutaneous xenograft model was established to explore the integrative function of FAM3C in glioma growth in vivo." (PMID 39629744, 2024). "Hence, FAM3C may be chosen as a potential biomarker for clinical diagnosis and a promising therapeutic target in glioma treatment." (PMID 39629744, 2024). "Herein, our study investigated whether FAM3C contributes to glioma cell proliferation, invasion, apoptosis, and EMT by mediating the Notch signaling pathway, thus offering novel avenues for clinical diagnosis, prognostic assessment, and potential targeted therapy in gliomas." (PMID 39629744, 2024). "We utilized open‐source bioinformatics tools and platforms to analyze the transcriptional expression levels, prognosis, and correlation with clinical variables of FAM3C in gliomas, and subsequently, to hypothesize its potential molecular functions and possibly associated signaling pathways." (PMID 39629744, 2024). "Subsequent examination of the CGGA database further corroborated these findings, demonstrating a positive correlation between FAM3C expression levels and the pathologic WHO classification of gliomas." (PMID 39629744, 2024). "Thus, it is evident that elevated FAM3C expression fosters the proliferation, invasion, apoptosis, and EMT of glioma cells." (PMID 39629744, 2024). "Our results revealed a significant increase in FAM3C expression across different grades of glioma compared to normal brain tissues, with expression levels positively correlated with the pathological WHO grading of gliomas." (PMID 39629744, 2024).
hyperglycaemia (2 papers, 2017 to 2019). "Hepatic FAM3C overexpression improves insulin resistance, hyperglycemia and steatosis of obese mice." (PMID 29285313, 2017). "In conclusion, FAM3C is a new hepatokine that activates HSF1-CaM-Akt pathway to ameliorate hyperglycemia of type 1 diabetic mice by suppressing hepatic gluconeogenesis in an insulin-independent manner." (PMID 29285313, 2017). "Hepatic FAM3C overexpression activated HSF1-CaM-Akt pathway to repress gluconeogenic gene expression and ameliorate hyperglycemia of type 1 diabetic mice." (PMID 29285313, 2017). "In the current study, we provided new evidences that FAM3C activated HSF1-CaM-Akt pathway to repress hepatic gluconeogenic gene expression and attenuate hyperglycemia of type 1 diabetic mice." (PMID 29285313, 2017). "FAM3C, a member of FAM3 gene family, has been shown to improve insulin resistance and hyperglycemia in obese mice." (PMID 29285313, 2017). "In the current study, we demonstrated that hepatic FAM3C or HSF1 overexpression repressed gluconeogenic gene expression and attenuated hyperglycemia of type 1 diabetic mice." (PMID 29285313, 2017). "One is that although FAM3C activates HSF1-CaM pathway to activate Akt independent of insulin in cultured hepatocytes, whether it can suppress hepatic gluconeogenesis to improve hyperglycemia of type 1 diabetic mice remains unknown." (PMID 29285313, 2017).
lung adenocarcinoma (2 papers, 2021 to 2023). A carcinoma that arises from the lung and is characterized by the presence of malignant glandular epithelial cells. "First, comprehensive analyses on TCGA pan-cancer transcriptome revealed the high expression of FAM3C both in lung adenocarcinoma and squamous cell carcinoma." (PMID 36632230, 2023). "Notably, FAM3C expression is elevated in malignant lung tissues (lung adenocarcinoma, LUAD; and lung squamous cell carcinoma, LUSC) compared to the non-malignant tissues based on The Cancer Genome Atlas (TCGA) database." (PMID 36632230, 2023). "Of 516 lung adenocarcinoma (LUAD) cases, 18 (3.5%) had MET and 9 (1.7%) FAM3C CN amplification, 8 deriving from the MET amplification group." (PMID 33596971, 2021).
lung squamous cell carcinoma (2 papers, 2021 to 2023). "Of 501 lung squamous cell carcinoma (LUSC) cases, 8 (1.9%) indicated MET, out of these 6 (1.4%) also FAM3C CN amplifications." (PMID 33596971, 2021).
Myeloma (2 papers, 2021 to 2023). "Myeloma cells also frequently upregulated FAM3C, a ligand of the inhibitory KIR2DL3 receptor expressed on NK and γδ T-cells." (PMID 34845188, 2021).
osteoporosis (2 papers, 2011 to 2016). A condition of reduced bone mass, with decreased cortical thickness and a decrease in the number and size of the trabeculae of cancellous bone (but normal chemical composition), resulting in increased fracture incidence. "SNPs in associated regions on chromosomes 7 and 11 are proximal to genes PLEKHB1 (chr11), FAM3C (chr7), and WNT16 (chr7), and the latter has been associated with bone mineral density, osteoporosis, and fracture risk." (PMID 27325353, 2016).
type 2 diabetes (2 papers, 2017 to 2022). "Clearly, FAM3C represents a new target for treating type 2 diabetes." (PMID 29285313, 2017).
anemia (1 paper, 2023). A reduction in the number of red blood cells, the amount of hemoglobin, and/or the volume of packed red blood cells. "In order to investigate if anemia was caused by a malfunction in the erythroid lineage due to ILEI overexpression, we next examined the effects of Vav1-driven overexpression of the Fam3c/ILEI transgene on overall fitness and blood parameters." (PMID 37713409, 2023).
glioblastoma (1 paper, 2024). The most malignant astrocytic tumor (WHO grade IV). "Initial analysis revealed a notable upregulation of FAM3C expression in glioblastoma compared to normal brain tissues, as evidenced by RNA‐seq data sourced from GTEx and TCGA datasets within the GEPIA database." (PMID 39629744, 2024).
metastatic disease (1 paper, 2023). "Given these distinct lines of evidences, aberrant FAM3C expression is likely to represent a prognostic biomarker for predicting the risk of developing metastatic disease, and opens an opportunity to investigate RalA inhibitors as potential targeted therapies." (PMID 36632230, 2023).
migraine (1 paper, 2025). "Six proteins were significantly upregulated in migraine with a >1.5 fold change compared to controls and Padj < 0.05 (FAM3C, GOLM1, PSA7, ENPP2, DSG2, TFRC); 3 proteins were significantly downregulated (FGL1, CAH2, AMYP)." (PMID 40852402, 2025).
Obesity (1 paper, 2020). Accumulation of substantial excess body fat. "Together, these findings suggest that FAM3C epigenetic dysregulation could have shorter- and also longer-term impacts on the development of obesity." (PMID 33003475, 2020).
psoriasis (1 paper, 2023). An autoimmune condition characterized by red, well-delineated plaques with silvery scales that are usually on the extensor surfaces and scalp. "Analyses of human psoriatic skin and studies in genetically engineered mouse models revealed that FAM3C/ILEI contributes to psoriasis by controlling keratinocyte hyperproliferation, differentiation, and neutrophil recruitment and identifies uPA, a regulator of ILEI secretion, as a druggable target." (PMID 37226685, 2023).
stomach cancer (1 paper, 2023). "However, we found that FAM3C is prominently expressed in neutrophils in gastric tumor tissues and is detected weakly in tumor cells." (PMID 37056931, 2023).
type 1 diabetic (1 paper, 2017). "FAM3C overexpression increased the protein levels of HSF1, CaM and phosphorylated Akt (pAkt) with the reduced PEPCK and G6Pase protein levels in type 1 diabetic mouse livers." (PMID 29285313, 2017).
tumor (36 papers, 2011 to 2025). "Mounting evidence underscores FAM3C's overexpression in diverse human cancers, strongly linked to tumor initiation, invasion, metastasis, and poor survival." (PMID 39629744, 2024). "Our results showed that FAM3C was highly expressed in HNSC tumor tissues and high expression of FAM3C was strongly associated with poor prognosis." (PMID 37704682, 2023). "For example, recent studies have shown that increases in FAM3C protein levels are closely associated with tumor formation, invasion, metastasis, and poor survival, suggesting that FAM3C may serve as a potential biomarker and therapeutic target in cancer." (PMID 38895099, 2024). "Although CD320 is known to be associated with B-cell survival and proliferation, and FAM3C is a known inducer of osteoblast differentiation, their effect on the tumor microenvironment and their role in MM progression is subject to further research." (PMID 41056512, 2025). "In vitro knockdown of ALDH1A3 or associated genes such as FAM3C, MCC, PMEPA1, and IRS2 reduced tumor invasion, while in vivo reduction similarly curbed tumor growth and metastasis." (PMID 40781158, 2025). "Multiple cancer cell models and orthotopic animal model experiments have demonstrated a role for Fam3C in tumor progression and metastasis." (PMID 41247074, 2025). "Tumor cells can also induce neutrophils through TGFβ1, activate the Smad2/3 signaling pathway, leading to increased FAM3C production." (PMID 40568576, 2025). "Collectively, these results strongly suggest that tumor cells increase FAM3C levels through TGFβ1-Smad2/3 pathway in neutrophils during their interaction, and FAM3C-mediated tumor cell EMT is through JNK-ZEB1/Snail signaling activation." (PMID 37056931, 2023). "It is significant that FAM3C is present in both the primary tumor as well as the secretome as part of the circulatory EVs." (PMID 36632230, 2023). "Resected lungs were washed and stained in Bouin's solution, and both microscopy and macroscopy analyses revealed gross disparities in intrapulmonary tumor burden of mice that were positively correlated to FAM3C status." (PMID 36632230, 2023). "In conclusion, our study demonstrates that tumor cells educate TANs via TGFβ1 to produce more FAM3C, which mediates tumor cell EMT." (PMID 37056931, 2023). "Mechanistically, co-culture with tumor cells increases FAM3C levels in neutrophils regulated by TGFβ1-Smad2/3 signaling activation, and FAM3C promotes tumor cell EMT through JNK-ZEB1/Snail pathway." (PMID 37056931, 2023). "As expected, the cytokeratin positive FAM3C_kd derived tumor nodules exhibit negligible FAM3C expression." (PMID 36632230, 2023). "Functional phenotype of endogenous FAM3C and tumor-derived EVs (TDEs) were further investigated using various biological approaches in RNA and protein levels." (PMID 36632230, 2023). "Mechanically, tumor cells educated neutrophils via TGFβ1 to produce more FAM3C through Smad2/3 signaling activation, and FAM3C promoted tumor cell EMT through JNK-ZEB1/Snail signaling pathway." (PMID 37056931, 2023). "Here, we found that BMI1, CD44, SOX2, OCT4, UBE2C, CXCR4 CSCs marker genes are significantly upregulated, while IGF1-R, KLF4, ALDH1A1, CD133, FAM3C are downregulated in the tumor core vs healthy mucosa of 24 patients with OSCC." (PMID 38096163, 2023). "After treatment with SP600125, an inhibitor for JNK signaling, the expression of E-cad, Vim, ZEB1 and Snail mediated by FAM3C was reversed, suggesting that FAM3C promotes tumor cell EMT via JNK-ZEB1/Snail signaling activation." (PMID 37056931, 2023). "We next investigated the potential molecular signaling responsible for tumor cell-mediated up-regulation of FAM3C in neutrophils during their crosstalk." (PMID 37056931, 2023). "By focusing on the epithelial compartments of the primary tumors and metastases, there was an increase of FAM3C expression in most of the tumor clusters of the metastases." (PMID 36632230, 2023).